CTLA4 (cytotoxic T-lymphocyte associated protein 4)
Diseases named in the same sentence as CTLA4 in open-access papers (continued):
Sharing a sentence is not in itself a finding about the gene and the disease.
cancer (continued). "In conclusion, our findings suggest that CTLA-4 expression correlates with the worst prognostic factors in the IPS for advanced-stage CHL, supporting the notion that immune checkpoints play a role in cancer progression." (PMID 38978137, 2024). "Ipilimumab (anti-CTLA4) is the only immune checkpoint inhibitor (ICI) non-targeting PD(L)-1 that has been approved so far by the FDA for MSI-H cancer, namely, CRC in combination with nivolumab." (PMID 38254772, 2024). "On the other hand, if anti-cancer therapy is central to cancer therapy in metastatic NSCLC, then we contend that a different design comparing anti-CTLA4 + anti-PD1/L1 with anti-PD1/L1 alone or with anti-PD1/L1 + standard chemotherapy would be more defining and revealing." (PMID 38539487, 2024). "Additionally, it was illustrated that ANKRD27 expression showed a positive correlation with the level of inhibitory immune checkpoints, such as CD274, PDCD1, CTLA4, and HAVCR2, across various types of cancer." (PMID 39834932, 2024). "Therefore, further Pearson analysis was conducted to investigate the correlation between GPR65 and common cancer immune checkpoint inhibitors, such as CD200R1, CD47, HAVCR2, TIGIT, CTLA4, LAG3, and PD1." (PMID 38218960, 2024). "Checkpoint inhibitors like anti-PD-1 and anti-CTLA4 are immunostimulatory antibodies, and their blockade extends the survival of some but not all cancer patients." (PMID 38263981, 2023). "Proteins involved in immune checkpoint pathways, such as CTLA4, PD1, and PD-L1, have become important targets for cancer immunotherapy; however, development of small molecule drugs targeting these pathways has proven difficult due to the nature of their protein–protein interfaces." (PMID 37122540, 2023). "Though PD-1/PDL-1 and CTLA-4 checkpoint blockades have dominated the clinical development of immune therapy for cancer, there has long been the appreciation that these are not the only proteins that function as immune checkpoints in human biology." (PMID 37296902, 2023). "Ipilimimab, an ICI targeting CTLA4, was the first ICI to be approved for the treatment of cancer." (PMID 37513979, 2023). "Furthermore, positive correlations of PRC1 and some immune checkpoint genes (CD274, CTLA4, HAVCR2, LAG3, PDCD1, PDCD1LG2, TIGIT, and CD86) were observed in several cancers, especially BLCA, BRCA, KIRC, LUAD, LIHC, PRAD and THCA." (PMID 37563591, 2023). "The number of infiltrating CD8+ T cells in cancer mucosa did not significantly differ according to cancer stage; however, the levels of PD-L1 and CTLA-4 expression were increased in CD8+ T cells." (PMID 37153541, 2023). "In addition, we also itemized the correlations between TAGLN2 and the major immune checkpoints in pan-cancer, including LAG3, PDCD1, CTLA4, CD274, and TIGIT." (PMID 37476180, 2023). "Besides CTLA-4, now several immune checkpoint receptors (ICRs), such as PD‐1, LAG3, TIM-3, B7‐H3, and diacylglycerol kinase α, have been also identified to treat cancer patients effectively." (PMID 36109471, 2023). "Immune checkpoint inhibitors (ICIs) act specifically to block CTLA4 and PD-1, so we compared GzmA and GzmB expression in CD57+ CD4+ T cells in blood obtained from cancer patients before and after treatment with anti-CTLA4/PD-1 (ipilimumab/nivolumab) combination checkpoint inhibitor therapy." (PMID 37161048, 2023). "The PD-1/PD-L1 inhibitor operates by blocking the interaction between PD-1 located on T cell membranes and the overexpressed PD-L1 on cancer cell membranes, while CTLA-4 inhibitor works by blocking the binding of B7 on antigen-presenting cells to CTLA-4 in T cells." (PMID 37926852, 2023). "Ipilimumab, an anti-CTLA4 monoclonal antibody, has received regulatory approval from agencies such as the Food and Drug Administration (FDA) and the European Medicines Agency (EMA) for the treatment of cancer treatment, including metastatic CRC)." (PMID 37601778, 2023).
cancer (continued). "Additionally, the Tc cells express a protein, receptor protein cytotoxic T lymphocyte antigen four (CTLA4), which binds to ligands CD80 and CD86 expressed by antigen-presenting cells and cancer cells." (PMID 36902456, 2023). "The same phenotype has been observed in cancer: Nrp-1 expression on CD8+ T cells was accompanied by elevated expression of CD44, CD69 and CD25, but also by several co-inhibitory molecules such as PD-1, CTLA-4, Lag-3 and Tim-3." (PMID 38019895, 2023). "The lack of costimulatory signals due to the PD-1/PD-L1 and CTLA-4 hyperactivation makes the capacity of T cells to target cancer useless." (PMID 37185406, 2023). "While immunotherapies directed against CTLA-4 and PD-1/PD-L1 have shown remarkable success in treating certain cancers, they are not effective for all patients and many of them do not benefit from it." (PMID 38162657, 2023). "The results demonstrated that SERPINE1 expression was positively correlated with the expression of most inhibitory immune checkpoints, including CD274 (PD-L1), PDCD1 (PD-1), CTLA4, and HAVCR2 (TIM-3) in most cancers, especially GBM-LGG, KIPAN, UVM, PAAD, and COAD-READ." (PMID 37680718, 2023). "Therefore, the application of anti-CTLA4, anti-PDCD1 (PD-1) and anti-CD274 (PD-L1) agents is becoming a promising therapeutic option in several types of cancers." (PMID 36845098, 2023). "Indeed, targeting CTLA-4, TIGIT, PD-1, GITR and other co-inhibitory receptors to limit the function of Tregs possibly is an effective cancer treatment." (PMID 37671150, 2023). "Immune checkpoint inhibitors (ICIs) employed for cancer therapy include PD-1 (pembrolizumab, nivolumab, cemiplimab, dostarlimab), PDL-1 (atezolizumab, avelumab, durvalumab), CTLA-4 (ipilimumab, tremelimumab), and the recently approved LAG-3 antibodies (relatlimab)." (PMID 37342323, 2023). "In contrast, cancer immunotherapy can recover the normal body’s function of antitumor immune response via regulating the expression of checkpoint genes, such as TNFSF9, PDCD1 and CTLA4." (PMID 37013511, 2023). "Studies have shown that antibodies against CD274, CTLA-4, and PDCD1 (immune checkpoint molecules) could promote antitumor T cell activity and improve clinical outcomes in various cancers." (PMID 37851374, 2023). "Moreover, simultaneous expression of inhibitory co-receptors (such as PD-1, CTLA-4, TIM-3) is correlated with increased T cell dysfunction in cancer and disease progression." (PMID 36826125, 2023). "Unlike anti-PD-1 antibodies, the antibodies against CTLA-4 act at a stage where T cells are activated after being presented with the cancer antigens via antigen presenting cells." (PMID 36672492, 2023). "CTLA4, LAG3, and PDCD1 are important targets for cancer ICI therapy." (PMID 38333724, 2023). "Blocking antibodies, particularly PD-1 and CTLA-4, have shifted the paradigm of cancer therapy; however, many patients with cancer do not respond and develop resistance to ICIs." (PMID 36798830, 2023). "Moreover, we found that KIF18A had a positive correlation with immune checkpoints, such as PD-1, PD-L1, CTLA4, TIGIT, LAG3, HAVCR2, and PDCD1LG2 in a great many cancers." (PMID 36830695, 2023). "Advances in cancer immunotherapy with an immune checkpoint inhibition mechanism (e.g., ipilimumab, an anti-CTLA-4 inhibitor) have not shown a survival benefit in patients with CRPC." (PMID 37511873, 2023). "By the end of 2022, at least seven types of ICIs, including PD-1 inhibitors (Nivolumab, Cemiplimab, Pembrolizumab), PD-L1 inhibitors (Avelumab, Durvalumab, and Atezolizumab) and CTLA-4 inhibitor (Ipilimumab) have been approved by food and drug administration (FDA) for the various cancer therapies." (PMID 37735656, 2023). "Here, we analyzed the association of FAM110A with more than 40 immune checkpoint genes in pan-cancer based on the TCGA database and verified the correlation of FAM110A between several immune checkpoint genes, including PD-1, PD-L1, LAG-3, and CTLA-4 in the TIMER 2.0 database." (PMID 36923407, 2023).
cancer (continued). "Antibodies against PD1, PD-L1 or CTLA4 have achieved substantial success in the treatment of some cancers, but they are not effective in a large cohort of cancer patients." (PMID 37313600, 2023). "CTLA-4 has been generally recognized as the most compelling target immunotherapy, and ipilimumab (anti-CTLA4) has radically and significantly improved the clinical outcomes of patients with advanced cancer." (PMID 37768204, 2023). "Also, they can modulate the expression of immune checkpoint molecules such as PD-1, PD-L1 (programmed cell death ligand 1), PD-L2 (programmed cell death ligand 2), CTLA-4 ), CD47, etc., in several cancers." (PMID 37761948, 2023). "Researchers have found a number of immune checkpoint signals in cancers that could confer strong immunosuppression on cancer cells by combining ligands with inhibitory immunoreceptors, such as PD-1, TIGIT, CTLA-4, BTLA, LAG3, and TIM3." (PMID 36895440, 2023). "The adaptive immune system’s role in cancer immunosurveillance is well established and plays a crucial role for most cancer immunotherapies such as immune checkpoint inhibitors for example anti-PD1 (pembrolizumab and nivolumab) and CTLA-4 inhibitors (ipilimumab)." (PMID 37143649, 2023). "Furthermore, a notable heterogeneity was observed in the relationship between Eph receptors/EFN ligands and main checkpoints (CD274, PDCD1, CTLA4, and LAG3) in different types of cancer." (PMID 37637034, 2023). "Currently, the essential strategy for cancer immunotherapy aims to block the coinhibitory receptors, such as PD1 and CTLA4, which is no doubt an important advance for cancer treatment." (PMID 38127899, 2023). "Interestingly, the findings suggested a correlation between HIF1AN in breast malignancy and PDCD1, LAG3, CTLA4, and GZMB of T cell exhaustion as well as chemokine ligand CCL2 of TAMs." (PMID 36816977, 2023). "Subsequently, we presented scatter plots showing a significant negative correlation between PRR7-AS1 and PD1, PDL1, and CTLA4 expression in different cancer types." (PMID 37091809, 2023). "The rationale behind inhibiting CTLA-4 for treating cancer is not a novel idea but has been reported back in 1996." (PMID 39086690, 2023). "Nevertheless, cancer-cell-intrinsic CTLA-4 expression has never been previously analyzed in mammospheres." (PMID 36901916, 2023). "Therefore, the interaction of CTLA-4 and CD80/CD86 inhibits the T cell activation signal, resulting in the suspension of the cancer-immunity cycle." (PMID 36980950, 2023). "The large number of immune checkpoint pathways beyond PD-1/PD-L1 and CTLA4 has not been as closely examined for their role in modulating peripheral T cell tolerance in the setting of cancer and atherosclerosis." (PMID 38213548, 2023). "Inihibitors of mmune checkpoint molecules such as blocking antibodies against PD-1 and CTLA-4 are currently FDA approved and used routinely for the clinical management of cancer as monotherapeutic agents or in combination with other treatments and many more are currently in clinical trials." (PMID 37274739, 2023). "Here, we found that ML323 administration eliminates cancer stem cells increases CD8+ T cells infiltration simultaneously, and enhances the therapeutic efficacy of anti-CTLA4 antibody or 5-FU, demonstrating the great potential of ID1 as a dual-functional target." (PMID 37996458, 2023). "One group has demonstrated the activation of IFN response genes in cancer cells occurs, suggesting this may contribute to the efficacy of CTLA-4 blockade, such that CTLA-4 blockade fails in patients with defects in these genes." (PMID 36881480, 2023). "Advances in cancer immunotherapy with an immune checkpoint inhibition mechanism (e.g., ipilimumab, an anti-CTLA-4 inhibitor) have not shown a survival benefit for patients with CRPC." (PMID 37511873, 2023).
cancer (continued). "Therapeutic antibodies against immune checkpoint receptors, such as PD-1 and CTLA-4, along with adoptive transfer of genetically engineered chimeric antigen-receptor (CAR)-T cells, have demonstrated tremendous success in treating some cancers." (PMID 37638058, 2023). "Characterized by sustained upregulation of multiple checkpoint proteins (PD-1, TIM-3, CTLA-4, LAG-3), exhausted T cells are a distinct group of dysfunctional T cells with poor effector function that arise in response to chronic viral infections and cancer." (PMID 36826125, 2023). "In addition, AP3S1 was positively correlated with most immunosuppressive genes, including PD-1, PD-L1, CTLA4, LAG3 and TIGIT in most cancer types." (PMID 35874816, 2022). "ICIs which have shown to be effective in many types of cancer (anti-PD-1 mAb (pembrolizumab and nivolumab), anti-PD-L1 Ab (avelumab, durvalumab, and atezolizumab), and anti-CTLA-4 Ab (tremelimumab and ipilimumab)), are not equally effective in treating CRC." (PMID 35628540, 2022). "Although treatments targeting the immune checkpoints PD-1 and CTLA4 are successful in many cancers, not all patients benefit from them." (PMID 36386809, 2022). "It is notable that most immuno-suppressive genes were negatively related to m7G scores through 33 cancers, such as famous drug targets PD1 (gene: PDCD1, ≥30 cancers), CTLA4 (gene: CTLA4, ≥27 cancers) and the next immune checkpoint receptor LAG3 (gene: LAG3, ≥27 cancers)." (PMID 36092891, 2022). "In the vast majority of 33 cancers, gene co-expression analysis showed that RIPK2 was positively correlated with the expression of immune checkpoint markers, such as PDCD1 (PD-1), CD274 (PD-L1), CTLA4 and TIGIT." (PMID 35508972, 2022). "Cancer cells can express regulatory ligands such as PD-L1, CD80/CD86, or Galectin-9 to provide a negative regulatory signal to T lymphocytes expressing their respective receptors PD-1, CTLA-4, and TIM-3, resulting in T cell exhaustion." (PMID 35159351, 2022). "Among them, anti-CTLA-4 and anti-PD-1/PD-L1 have been approved by the European Medicines Agency (EMA) and Food and Drug Administration (FDA), and they have been applied to various malignant tumors." (PMID 36171887, 2022). "One exposed a bi-component protein comprising the CTLA-4 extracellular domain and the CD95L extracellular domain, present in the form of a covalently bound and stable homo-hexamer, suitable for the treatment of a patient with cancer (WO2014106839)." (PMID 35301281, 2022). "One recent clinical study found that the expression of BTNL2 and other immune checkpoint molecules, including CTLA-4, was increased following anti-PD-1 therapy, further suggesting that BTNL2 may represent a novel mechanism of cancer immune evasion." (PMID 35017553, 2022). "Blocking the interaction between CTLA-4 and its ligand facilitates T cells to recognize and kill cancer cells, and does not deplete FOXP3+ cells in human tumors." (PMID 35804953, 2022). "Tumor cells are known to be surrounded by reactive non-neoplastic cells that are unable to recognize and kill cancer cells due to the deregulation and overexpression of immune checkpoint proteins such as PD-L1, CTLA4, TIM-3, LAG3." (PMID 36551575, 2022). "CCNA2 was positively correlated with expressions of CD274, CTLA4, HAVCR2, LAG3, PDCD1, and TIGIT in most cancer types, which indicated the CCNA2 expression may act as a marker after immunotherapy." (PMID 35480884, 2022). "Although there is a significant amount of animal- and cell-based evidence supporting the relationship between immune checkpoint inhibitors (anti-PD-1, anti-PD-L1, anti-CTLA-4) and cancers, no pan-cancer analysis is available." (PMID 36147250, 2022). "Additionally, studies have indicated an association between clinical immune therapy effects and prognoses and the expression of immune checkpoint genes, including CTLA-4 and TIGIT, in various cancers." (PMID 36614956, 2022).
cancer (continued). "A myriad of ICs has been outlined and explored in cancer in past decades, encompassing but not restricted to PD-1, CTLA-4, LAG3, TIM3, T cell immunoreceptor with Ig and ITIM domains (TIGIT), and BTLA." (PMID 36510217, 2022). "In particular, cancer immunotherapy approaches based on the blockade of inhibitory immune checkpoints, such as PD-1, CTLA-4, and PDL-1, have shown promise in clinical settings and are being recognized for their capacity to reinstate antigen-specific CD8 T cell attack on cancers." (PMID 34922008, 2022). "In addition, we studied the relationship between the expression of KCC2 (SLC12A5) and NKCC1 (SLC12A2) in pan-cancer and immune checkpoint genes, including SIGLEC15, IDO1, CD274, HAVCR2, PDCD1, CTLA4, LAG3, and PDCD1LG2." (PMID 35372048, 2022). "CTLA-4 acts as a negative modulator of T-cell effector activity, making it an appealing target for cancer treatment." (PMID 36119533, 2022). "The CAFDL signature was significantly positively associated with TGFB1, CD276, CD40, VEGFA, VEGFB, etc., but showed significantly negative correlation with immune checkpoints (such as CD274, PDCD1, CTLA4, TIGHT, and HAVCR2) and anti-cancer immune regulators (IFNG, IDO1, and GZMA)." (PMID 35967425, 2022). "Emerging immunotherapy, including anti-CTLA4, anti-LAG3, anti-PD-1, and anti-PD-L1 antibodies, has been proven to be efficacious and increased the survival rate of patients with several advanced cancers, including metastatic osteosarcoma patients." (PMID 36276293, 2022). "Furthermore, this enhances the sensitization of cancer cells to the anti-CD40, anti-CTLA-4, and anti-PD-1 combination immunotherapy." (PMID 36072957, 2022). "In conclusion, the accumulation of Tregs with high expression of CTLA-4 and PD-1 in TDLNs and metastatic LNs in HNSCC showed by our study suggests that TDLNs are characterized by an immunosuppressive milieu that can, in turn, favour cancer progression." (PMID 35714487, 2022). "While immune checkpoint inhibition has produced meaningful therapeutic effects in many cancer types, clinical trials of anti-CTLA4 or anti-PD1 have not shown a clear advantage in PC patients." (PMID 35924159, 2022). "Furthermore, the PARP inhibitors can also enhance the anticancer activity of PD-1/PD-L1 or the CTLA-4 inhibition, demonstrating that the immunogenic effects of PARP can also be exploited for cancer therapy." (PMID 36555812, 2022). "Immune-related arthritis (from CTLA-4, PD-1, or PD-L1 inhibitors) responds well to methotrexate and does not seem to increase cancer progression." (PMID 36081549, 2022). "James Allison of the United States and Tasuku Honjo of Japan were awarded the 2018 Nobel Prize in Physiology or Medicine for their contributions to the discovery of negative immune regulation, also known as CTLA4 and PD-1, as cancer treatments." (PMID 36248998, 2022). "For AGC patients, anti-CTLA-4 and anti-PD-1/PD-L1 monoclonal antibodies cannot acquire satisfactory curative effect without the assistance of other cancer treatments." (PMID 36189223, 2022). "As anti-CTLA-4, anti-PD-1, and anti-PD-L1 antibodies interrupt these co-inhibitory signal pathways and restore the function of cytotoxic CD8+ T cells, these antibodies have been used to treat many chemo-resistant cancers." (PMID 35159059, 2022). "Cancer patients currently benefit tremendously from both anti-PD1 and anti-CTLA-4 immunotherapies." (PMID 35311149, 2022). "Among cancer immunotherapies, immune checkpoint blockade (ICB) which targets cytotoxic T lymphocyte antigen 4 (CTLA-4) or the programmed cell death 1 (PD1)–programmed cell death ligand 1 (PD­L1) axis has been approved for the treatment of several different cancer types." (PMID 35874784, 2022). "Blockade of the PD-1 or CTLA-4 axes in OAC and other cancer types has been the most investigated." (PMID 35366537, 2022). "The enrichment of CTLA4 and IL4I1 were consistent with their functions in cancer." (PMID 35778697, 2022).